CD44 (CD44 molecule (IN blood group))
Diseases named in the same sentence as CD44 in open-access papers (continued):
Sharing a sentence is not in itself a finding about the gene and the disease.
tumor (continued). "In this study, we found that KCNN4 was highly expressed in LCSCs, where KCNN4 promoted the ratio of the CD133+CD44+ subpopulation, the expression of stem cells transcription factors, and the sphere formation ability in vitro, as well as increased tumor incidence and tumor growth in vivo." (PMID 35805963, 2022). "Serum exosomal CD44 concentration was positively correlated with tumor burden in lymph nodes." (PMID 35359362, 2022). "On the other hand, CD44 was validated as a key regulator of WNT, PI3K/AKT and MAPK/ERK signaling pathways, thereby supporting our hypothesis that PCF11 is a potential novel transcriptional target that underpins CD44/HA-promoted tumor cell invasion." (PMID 35756640, 2022). "Combined with the literature, it was concluded that CD44 is a class I transmembrane glycoprotein that can adhere to the extracellular matrix and bind to hyaluronic acid and collagen, playing an important role in the distant metastasis of tumours." (PMID 36316684, 2022). "In addition, we performed CD44 and MAL costaining of these samples and found similar expression patterns for MAL; CD44, a tumor stem marker, was expressed at low levels in early GC and at high levels in advanced GC." (PMID 35093120, 2022). "While our previous work demonstrated that CD44 homophilic binding mediates tumor cell aggregation, in this study we propose that CD81 interacts with CD44 to promote intracellular CD44-CD81 heterodimer formation and possibly intercellular tetramer formation between two neighboring cells." (PMID 36193887, 2022). "Interestingly, it is known that the expression of CD44 isoforms containing exon v6 is a prerequisite for c-Met activation by its ligand HGF in several tumor cells and in primary cells." (PMID 35488271, 2022). "To evaluate the expression level of MRE11 and CD44 in OSCC patients, we analyzed the two proteins by immunohistochemical staining, which showed that a positive correlation between MRE11 and CD44 protein expression was observed in OSCC tumor tissues (p < 0.001)." (PMID 35629265, 2022). "TNFSF9, CD276, CD40, CD274, and CD44 expression was downregulated in cluster 6 (hypoxic tumor)." (PMID 36685583, 2022). "We, therefore, asked whether CD44 in tumor cells would regulate cellular stiffness to inhibit heterotypic CIC formation." (PMID 35436988, 2022). "The relationship between Sp1 and CD44 levels was studied in normal and tumor clinical tissues." (PMID 35034634, 2022). "CD44, the surface receptor regulating cancer cell adhesion critical for colonization and invasion, also markedly increased with tumor injection, as shown in the PBS and dKLA groups compared to that in the WT group, whereas this increase was inhibited by TAMpep or TAMpepK treatment." (PMID 35216272, 2022). "Notably, the expression of CD44 was found to positively correlate with the expression of phosphorylated AKT in the tumor tissues of OSCC patients (p = 0.020)." (PMID 35629265, 2022). "Although chemical Pin1 inhibitors elicit potent antitumor effects against several human cancers, their inhibitory impact on the tumorigenic capacity of CD44+CD133+ tumor-initiating Caco-2 cells was unknown." (PMID 35433695, 2022). "Furthermore, CD44 also plays a critical role in leukocyte recruitment, T-cell activation, tumor progression and metastasis, as well as in transmission of signals mediating hematopoiesis and apoptosis." (PMID 36042265, 2022). "In addition, our results also support a functional role of this CD44/TF regulatory axis in providing tumor cells with enhanced procoagulant activity and increased metastatic colonization abilities." (PMID 35805061, 2022).
tumor (continued). "CD44 is a transmembrane glycoprotein that mediates cell-cell or cell-matrix interactions with hyaluronic acid (HA) as the main ligand, and is strongly involved in tumor progression, apoptosis evasion, multidrug resistance, and cell invasion." (PMID 35204054, 2022). "The mesenchymal cluster included a stem-cell like profile with upregulation of CD44 and downregulation of CD24, which is consistent with the simultaneous presence of EMT and stem-like features of tumour cells associated with metastatic potential of cancer cells." (PMID 35493092, 2022). "Indeed, we evaluated the effect on the expression of CD44 antigen, a molecule involved in adhesion, and therefore in cell spreading in tumor invasion." (PMID 35328491, 2022). "This novel tumor model has great potential for preclinical drug testing and could be used to further understand the mechanisms of CD44-positive cancer cell progression in an HA-rich TME." (PMID 35198956, 2022). "The smallest standard CD44 isoform (CD44S) is ubiquitously expressed mainly on leukocytes, while variant isoforms (CD44v1–v10) are expressed in several epithelial tissues and larger ones during tumor progression." (PMID 35456670, 2022). "Investigation of the level of CD44 expression in the tumor tissues may be useful to predict the effectiveness of BCNU wafers in prolonging survival for patients with GBM." (PMID 35624954, 2022). "Both matrix metalloproteinases and CD44 are critical for tumour invasion." (PMID 35264209, 2022). "However, in the time-independent study, a significant increase of tumour CD4+ T cells and increased expression levels of CD44 marker on these cells were observed in nsECT4-treated compared to untreated tumour-bearing mice." (PMID 36551739, 2022). "However, CD44 can also act as a tumour suppressor, for example when cells reach confluent growth conditions, and thus inhibit cell growth." (PMID 35552415, 2022). "CD44 can regulate the malignant processes such as angiogenesis and tumor growth." (PMID 35626430, 2022). "To determine the genetic signature of the catulin GFP + cells we isolated, and FACS sorted GFP + CD44 + and GFP-CD44 + cells from 3 independent tumors formed after the injection of the MDA-MB-231-Cat-GFP reporter cell line using CD44 as an additional tumor cell marker to increase sort purity." (PMID 35879327, 2022). "Previous studies have reported that NTP treatment can oxidize proteins on the cancerous cell surface (e.g., CD47, CD44), which may interrupt tumor survival or immune evasion." (PMID 36176603, 2022). "Moreover, CD44 stimulates pathways that initiate and promote tumour cell proliferation and epithelial-to-mesenchymal transition." (PMID 35296132, 2022). "As a matter of fact, CD44+/CD24+ pancreatic cancer cells that express epithelial-specific antigens appear to possess several stem-like properties that have led them to be considered as tumor-initiating cells." (PMID 36013184, 2022). "Interestingly, CD44 was a well-defined cancer stem cell (CSC) marker that was involved in tumor initiation, epithelial-mesenchymal transition (EMT), and therapy resistance in multiple types of cancer." (PMID 35493471, 2022). "The aberrant expression of CD44 in malignancy can lead to tumor extension and metastasis." (PMID 36230831, 2022). "Notably, this tissue-specific conditional silencing of CD44v6 resulted in long lasting effects on self-renewal and tumor growth associated with a positive feedback loop linking WNT3A signaling and alternative-splicing of CD44." (PMID 35982950, 2022). "Interestingly, CD44 has been shown to be expressed in the subpopulation of cancer stem cells (CSCs), which can reconstitute the tumor mass." (PMID 35785191, 2022). "Aberrant alternative splicing of CD44 is closely related to tumorigenesis and tumor progression." (PMID 35992805, 2022).
tumor (continued). "Our results indeed show that: (i) CD44 and TF are co-expressed in different human breast EMT+ tumor cell models, (ii) silencing CD44 diminishes TF at the RNA and protein levels, (iii) silencing CD44 decreases the coagulant activity and the metastatic seeding properties of EMT+/TF+ tumor cells." (PMID 35805061, 2022). "Furthermore, because CD44 is a critical receptor for the HA molecule, its amplification in tumor cells allows for more targeted drug delivery." (PMID 36080515, 2022). "HCT116CD133+CD44+ cells formed tumour spheres in vitro and continued to grow adherently in complete culture medium, indicating that they tolerated serum-free culture conditions, maintained the ability to proliferate and divide and had characteristics of stem cells rather than differentiated cells." (PMID 34281572, 2021). "Notably, the anti-tumor effect of 1 μg/mL of recombinant Eno1 proteins on MMT-based viability was suppressed when CD44 was silenced." (PMID 34373756, 2021). "CD44-induced epithelial-mesenchymal transition (EMT), however, is strongly correlated with cancer metastasis and is regulated by TGF-β1, and the anti-tumor effect could inhibit the expression of both CD44 and TGF-β." (PMID 33925400, 2021). "The secondary xenografted tumors were positive for CD44 and/or CD133, which mirrors the pattern seen in primary xenografts, suggesting that tumors derived from the secondary transplant of CD44+CD133+ cells into NSG mice retained similar phenotypic patterns to the primary tumor." (PMID 33994850, 2021). "CD44+/CD24− cells are identified as mesenchymal-like BCSCs that localize at the tumor margins and are to blame for metastasis, whereas ALDH+ cells are defined as differentiated epithelial-like BCSCs that are found in deeper sites of tumors and have more proliferative properties." (PMID 34575017, 2021). "Taken together these studies indicate that increased PGE2/EP4 signaling promote the tumor and mesenchymal activities of CD44+/CD24- breast CSCs; however, any corresponding effect on the more epithelial-like ALDH+ CSCs was not specifically assessed in the studies." (PMID 35127497, 2021). "Furthermore, following standard chemotherapy or endocrine therapy, the patients with a higher frequency of CD44-/CD24- tumor cells had a significantly shorter DFS than their corresponding patients with a lower frequency of CD44-/CD24- tumor cells." (PMID 34318746, 2021). "In our present research, HCT116CD133+CD44+ shcontrol cells and HCT116CD133+CD44+ shCldn7 cells can form typical cell spheres in serum-free medium and xenograft tumours in nude mice, indicating that CD133- and CD44-positive CRC cells had obvious stem cell-like phenotypes." (PMID 34281572, 2021). "We also show that CD44 cleavage promotes the migration of tumor cells." (PMID 33804427, 2021). "Thus, high CD44 expression in the tumor periphery of GBM (cut‐off value for the P/C ratio for R‐type: 18.0) will become a useful biomarker for predicting the degree of responsiveness to Bev." (PMID 33543833, 2021). "In this case, the thiolated HA covering not only served as protection for the drug-loaded cores, but it also allowed a more selective tumor-targeting thanks to the fact that HA is a molecule recognized by cluster of differentiation 44 (CD44), which is usually overexpressed in some neoplasms." (PMID 34201403, 2021). "For example, in hepatocarcinoma, IL-6 promotes the expression of CD44+, inducing tumor development." (PMID 33613850, 2021). "Finally, we attempted to improve tumor imaging with 89Zr-anti-CD44 by increasing the total dose of Ab injected." (PMID 33594192, 2021). "HA, with the interaction of CD44, contributed to the acceleration of tumor growth and metastases." (PMID 34571875, 2021).
tumor (continued). "We hypothesized that highly migratory cancer cells (such as E0771-M) with functional membranous CD44 are selected from the original tumor site to invade the HA-rich stromal area of tumor tissues." (PMID 34770956, 2021). "Finally, the researcher concluded that the HANGs had CD44 tumor targeting, reversing of MDR, and pH-responsive release effect for both drugs intracellularly." (PMID 35431911, 2021). "In experimental models of CRC, CD133+CD44+ cells are able to initiate tumours in nude mice." (PMID 34884696, 2021). "According to our findings, there was a significant and positive association between CD44 dysregulated expression and S phase of DNA cell cycle but a negative association with early apoptosis in CRC patients, suggesting CD44 role in apoptosis suppression reducing the tumor growth reserve." (PMID 34837915, 2021). "A similar pattern of DFS was observed in TNBC patients and those with a higher frequency of CD44-/CD24- cells had a high risk to develop progressive metastasis at 4 years post tumor resection regardless of chemotherapy." (PMID 34318746, 2021). "In order to better characterize these two cell populations, an additional FACs panel including a tumor marker (EpCAM), stem cell markers (CD44, CD24, and CD133) and mesenchymal‐like and mesothelial cell markers (CD90, podoplanin and mesothelin) was established." (PMID 34060699, 2021). "Among M‐type patients, those who show a high P/C ratio of CD44 expression may develop resistance to Bev relatively early after Bev therapy, resulting in a much more highly invasive tumor." (PMID 33543833, 2021). "Due to its widespread roles in promoting tumorigenesis, the inhibition of CD44 could impede tumour growth or sensitise tumour cells to therapy." (PMID 34944493, 2021). "Alternative mRNA splicing of CD44 is mediated by epithelial splicing regulatory protein 1 (ESRP1), and several reports have suggested that the upregulation of ESRP1 is associated with poor prognosis of tumours." (PMID 33210459, 2021). "Interestingly, CD44-mediated signaling regulates glycolysis as well as antioxidant-reduced glutathione to promote tumor growth and therapy resistance." (PMID 34680112, 2021). "CD44+ circulating tumor cells (CTCs) may act as a prognosis predictor in GC due to their close association with tumor metastasis and relapse." (PMID 33986804, 2021). "Correlation of high expression of ALDH1 with higher grading (p < 0.001) and high expression of CD44 with the localization of the neoplasm (p = 0.05), larger tumor size (p = 0.006), positive pN-category (p = 0.023), and advanced UICC stage (p = 0.002) was found." (PMID 33009929, 2021). "Remarkably, CD44 expression could be found mainly in the area of the tumor invasive front, which is in direct contact with the stromal cells surrounding the tumor and forms the tumor stem cell niche in HNSCC." (PMID 34307351, 2021). "When PHDM+anti-PDL1 was injected into the blood system, PHDM could accumulate into tumor sites and target tumor cells via CD44-mediated endocytosis and possess tumor chemotherapy." (PMID 33777920, 2021). "With its central role in cancer stem cells, CD44 may also be utilized as a prognostic marker of tumor regeneration following therapy." (PMID 34948786, 2021). "Tumor growth of CD44 + CSCs was obviously suppressed in vivo compared to CD44− CSCs." (PMID 34949193, 2021). "Simultaneously, CD44 also serves a similar role in attachment between tumor cells and exosomes." (PMID 34268118, 2021). "Increased levels of IL-6 have been observed with BLCA patients, and an activated cytokine IL-6 signaling provides a suitable microenvironment for CD44 induction where in immunocompetent mouse models blockade of IL-6 decreased CD44 expression attenuating tumor aggressiveness." (PMID 33672684, 2021). "Tumor cells express CD44 in a high-affinity state with the capacity for constitutive binding of HA." (PMID 33540535, 2021).
tumor (continued). "Concerning a correlation with disease characteristics, an association of high expression of ALDH1 with grading, high expression of CD44 with localization of the neoplasm, T- and N-category, and UICC stage, as well as high expression of SOX2 with perineural invasion was observed." (PMID 33009929, 2021). "A CD44 variant (CD44v) interacts with and stabilizes SLC7A11 at the plasma membrane, and therefore positively regulates the GSH levels and ROS scavenging in tumor cells, and in particular, in CD44-expressing colorectal and gastrointestinal CSCs." (PMID 33401748, 2021). "Furthermore, hyaluronic acid acts as a ligand to target tumor cells via CD44, which enables the hybrid particles to target solid tumors with highly expressed CD44 on the cell surface." (PMID 33659241, 2021). "It interacts with hyaluronan receptors (CD44) overexpressed in some tumor cells." (PMID 35479531, 2021). "Tumor cells have been reported to secrete excess amounts of hyaluronidases with the ability to cleave high molecular weight HA into smaller fragments (10–40 oligomers), which, in turn, promoted CD44 cleavage." (PMID 33540535, 2021). "In GC, the presence of CD44+ GC CTCs has been correlated to tumour metastasis and relapse." (PMID 33810350, 2021). "Next, based on the widely recognized view that CSCs are responsible for tumor metastasis, we assessed whether PRDX2 is functionally associated with the migration and invasion of CD133+CD44+ CSCs in vitro." (PMID 33819194, 2021). "It has been shown that disruption of the CD44/MMP9 complex inhibits tumor invasion." (PMID 34207884, 2021). "Furthermore, analysis of metastatic dynamics revealed that patients with a higher frequency (≥2%) of CD44+/CD24- CSCs usually developed distant metastasis earlier than those with < 2% of CD44+/CD24- and >19.5% of CD44-/CD24- tumor cells (the C1 group)." (PMID 34318746, 2021). "On the other hand, CD44 standard isoform (CD44s), which contains no variant exons, was revealed to be upregulated in several tumours, such as breast and liver tumours." (PMID 33210459, 2021). "Moreover, total amount of CD44 receptor detected with pan-CD44 antibodies was introduced as a marker of presence of tumour initiating cells regardless its splicing variability described later on." (PMID 34257584, 2021). "However, it is observed that in vivo results in an orthotopic tumor model; CD44 increased invasiveness and metastatic potential of cancer cells compared to the subcutaneous tumor model." (PMID 33672684, 2021). "RUNX3 is upregulated in CD44+ T cells, which serves as immunosuppressive role in tumor." (PMID 35187044, 2021). "Weak effector T cell responses in therapy-treated DIO mice were accompanied by low intratumoral concentrations of the T cell chemoattractant CCL5, heightened concentrations of pro-tumorigenic GM-CSF, and impaired proliferative capacity of CD44+CD8+ T cells in tumor-draining lymph nodes." (PMID 34064933, 2021). "In addition—led by our transcriptome analysis of non-tumour fatty liver in C3H/He mice, also highlighting a role for macrophages, we explored a specific candidate, namely CD44, with a suggested role as an upstream regulator of T cell homing." (PMID 34408183, 2021). "Moreover, GBM that primarily expresses CD44 at the margin compared to the tumor core has a worse prognosis than at tumors where CD44 is evenly distributed." (PMID 33805316, 2021). "Trem2 was not discerned by IHC in our FFPE liver tissues from C3H/He mice (data not shown).The number of CD44+ macrophages was strongly associated with the development of tumours and tumour number." (PMID 34408183, 2021). "During tumour progression, CD44 isoform expression is regulated by numerous signalling networks." (PMID 34944493, 2021). "In the past years, several studies indicated that HA and CD44 could regulate the expression of drug transporters and promote chemoresistance, leading to poor clinical efficacy in a wide spectrum of tumor cell types." (PMID 35154001, 2021).